CRP (C-reactive protein)
Diseases named in the same sentence as CRP in open-access papers (continued):
Sharing a sentence is not in itself a finding about the gene and the disease.
infection (continued). "Neither ESR nor CRP can be used as definitive indicators for differentiating between the types of infections analyzed." (PMID 40727523, 2025). "However, elevated CRP lacks specificity for VTE, as it is also observed in various inflammatory conditions, including infections, autoimmune diseases, and tissue injuries." (PMID 40723359, 2025). "CRP/ALB ratio levels are a good reflection of microvascular permeability, and there is a certain correlation between the levels and the degree of capillary leakage, which is one of the pathological features of organic infection." (PMID 41019129, 2025). "Similarly, high CRP (HR=2.157, 95% CI = 1.101–4.897, p=0.045) and high PCT (HR=1.943, 95% CI = 0.914–3.785, p=0.029) were independent factors predicting infection control rates." (PMID 40160471, 2025). "Combined detection of CRP and PCT has high clinical application value in the diagnosis and prognosis evaluation of fracture-related infections, providing more accurate guidance, particularly in predicting recovery and infection control." (PMID 40160471, 2025). "The use of WBC count as a primary infection marker is a further limitation, as more sensitive inflammatory markers like CRP or procalcitonin were not consistently available in the records." (PMID 41384024, 2025). "Timely use of inflammatory markers such as C-reactive protein (CRP) and procalcitonin was critical in recognizing infection despite the lack of classic features." (PMID 40895967, 2025). "Both in cases without (p ≤ 0.001) and with future infection progression (p = 0.005), CRP levels increased significantly from pre- to postoperatively." (PMID 40001448, 2025). "No indication of infection (normal values for CRP and leukocytes and for urine analysis) or further electrolyte shifts (normal values for sodium and potassium)." (PMID 41473459, 2025). "Background/Objective: Even in the absence of infection, prolonged rupture of membranes (PROM) has been associated with elevated neonatal C-reactive protein (CRP)." (PMID 41441318, 2025). "Conversely to intestinal infective diagnosis and bacteria diarrhea, PCT levels at ED admission showed the strongest predictive value for a final diagnosis of any infection (OR 1.793 [1.362–2.362]), performing better than WBC count (OR 1.009 [0.999–1.020]) and CRP levels (OR 1.003 [1.001–1.004])." (PMID 40150077, 2025). "Proteins like CRP, SERPINA3,SAA1, SAA2, and immunoglobulins were previously related to SARS-CoV-2infection in the literature,−, and their abundance increasesduring the infection and returns to their normal status after 3–4weeks postinfection." (PMID 40997940, 2025). "One such factor, C-reactive protein (CRP), is a nonspecific acute-phase protein produced in the liver in response to IL-6, increasing during inflammation, infection, and tissue damage." (PMID 41440513, 2025). "CRP and PCT levels were measured on postoperative days (POD) one, three, five, and seven, and compared among patients without infections, those with bloodstream infections, and those with other infections (urinary, bronchoalveolar lavage, or drain)." (PMID 41625880, 2025). "The first-line approach for diagnosing infections should remain CMTs, which include culture, microscopy, antigen detection, serology, polymerase chain reaction (PCR) testing, and non-specific infection biomarkers such as C-reactive protein and procalcitonin." (PMID 40901069, 2025). "Patients with a diagnosis of infection had a median CRP level of 52.5 mg/L [IQR: 14.7–140.0] compared to patients without infection [42.2 mg/L (IQR: 9.45–136.075)] (p = 0.381)." (PMID 40005357, 2025). "The patient received meropenem, levofloxacin, and azithromycin for infection control, which resulted in a reduction in body temperature, white blood cell count (15.7 to 11.38G/L), procalcitonin (PCT; 179.59 to 47.83 μg/L), C-reactive protein (CRP; 264 to 134 mg/L), and IL-6 (5,000 to 70.4 ng/L)." (PMID 40584717, 2025).
infection (continued). "Although C-reactive protein point-of-care tests (CRP-POCTs) are widely used for patients with signs of infection in many countries, they are not commonly used in the UK or German general practices." (PMID 39159989, 2025). "In both studies, the CRP level reflected both the infection and a large part of the non-infectious postoperative inflammation." (PMID 40565868, 2025). "Elevated CRP and ESR levels are almost universally present in postoperative infections." (PMID 40364274, 2025). "CRP was greater than 20 mg/L in 20/60 episodes with infection (33%) versus 7/82 episodes without infection (9%) (p=0.151), with sensitivity and specificity of 33.3% and 91.5%, respectively (Supplementary 3)." (PMID 40901476, 2025). "They did not observe significant differences for CRP, and due to the study design, patients with infection were not included in the study." (PMID 41230322, 2025). "Interestingly, citH3 was superior to CRP, WBC and cfDNA in predicting 28-day mortality in this cohort of patients with infection." (PMID 40731775, 2025). "A particular blood test, routine blood test, erythrocyte sedimentation rate (ESR), and C-reactive protein (CRP) revealed good results, with no sign of infection." (PMID 40373510, 2025). "Serial laboratory tests showed moderate anemia, with hemoglobin levels averaging 8.7 g/dL, decreasing C-reactive protein levels (from 2.18 to 0.69 mg/dl), normal blood glucose levels, unremarkable urinalysis, no infection and negative HIV and RPR serology." (PMID 40725788, 2025). "In previous analyses of this cohort, a substantial proportion of these culture-negative episodes were shown to have CRP responses indistinguishable from those observed in culture-positive episodes, suggesting many represent true infections." (PMID 40764898, 2025). "Due to its strong link with inflammation, CRP has gained widespread attention as a non-specific marker for tracking and assessing infections and inflammation as well as a prognostic tool for predicting cardiovascular events." (PMID 39940408, 2025). "Given the similar trajectories of BT, WBC and CRP within the first three days post-TAVR between patients with pronounced inflammatory reactions (ABTnf) and those with confirmed infections (ABTcf.), we aimed to integrate these factors into a risk stratification model." (PMID 39918726, 2025). "While systemic inflammatory markers—including C-reactive protein (CRP), interleukin-6 (IL-6), and procalcitonin (PCT)—demonstrate sensitivity to infection, their specificity for IAI in SAP is limited, as they also reflect sterile inflammation and pancreatic necrosis." (PMID 40852356, 2025). "Various inflammatory biomarkers, such as interleukin-6, tumor necrosis factor-alpha, and C-reactive protein (CRP), were studied as prognostic indicators in ACS, although they are influenced not only by the ACS itself but also by comorbidities, as infection or malignancy." (PMID 40843738, 2025). "In our cohort, several factors were associated with mortality on univariate analysis, including infection with MDR organisms, use of a non-tunneled catheter, concomitant pyocystitis, elevated CRP, qSOFA ≥ 2, and altered mental status at presentation." (PMID 41470207, 2025). "The results of the relevant literature do not provide a clear perspective regarding the value of CRP levels for predicting infection in patients with cancer." (PMID 40125102, 2025). "It must be taken into account that in our department, as well as in other arthroplasty departments, patients with relevant elevated CRP values were not operated on without further infection diagnostics." (PMID 40001448, 2025). "Second, some important clinical data, such as infection site, procalcitonin, and C-reactive protein, were not included in the study due to insufficient database information." (PMID 40761816, 2025). "Furthermore, infection monitoring by complete blood count (CBC) and CRP should be performed, as well as kidney function monitoring using creatinine." (PMID 41467576, 2025).
infection (continued). "Besides, r-hGH treatment also reduced the levels of infection indexes (PCT, CRP, and WBC) of patients." (PMID 39792837, 2025). "Serum markers of infection and inflammation including CRP, WBC, and PCT were not different between those with and without DSWI." (PMID 39920552, 2025). "This is consistent with our previous demonstration that 51.1% of culture-negative cases had increasing then decreasing CRP trajectories consistent with the standard response to infection (versus 64.5% of infections with an identified pathogen)." (PMID 40764898, 2025). "Previous studies have shown that patients with tunneled catheters often exhibit elevated serum CRP levels even in the absence of infection, suggesting chronic low-grade inflammatory activation." (PMID 41254792, 2025). "Patients were considered infection-free if they met all of the following criteria: absence of clinical signs of inflammation, serum values for CRP and ESR of <5 mg/L and <30 mm/h, respectively." (PMID 41322930, 2025). "If no CRP elevation is observed within 24 h of clinical symptoms, infection can likely be ruled out." (PMID 40507966, 2025). "A comprehensive literature search was performed across PubMed, Scopus, Web of Science, Cochrane Central Register of Controlled Trials (CENTRAL), and Google Scholar for studies evaluating the predictive value of CRP and NLR for postoperative infections following GI surgery." (PMID 41018345, 2025). "Despite initial antibiotic treatment, the infection persisted with slightly elevated C-reactive protein (CRP) and negative cultures." (PMID 39849416, 2025). "Routine blood tests, C-reactive protein, and general bacterial culture results were all normal, and there was no infection or pelvic effusion after surgery." (PMID 41415538, 2025). "In laboratory tests, we extracted six key clinical variables related to infection: neutrophil count (NEU), lymphocyte count (LYM), platelet count (PLT), C-reactive protein (CRP), neutrophil-to-lymphocyte ratio (NLR), and C-reactive protein-to-platelet count ratio (CRP/PLT)." (PMID 41413629, 2025). "A key observation was the similarity in the trajectories of BT, WBC, and CRP during the first three days post-TAVR between patients with confirmed infections (ABTcf.) and those receiving ABT without retrospectively confirmed infections (ABTnf)." (PMID 39918726, 2025). "CRP on day 4 is a reliable tool for ruling out infections due to its high negative predictive value (84.3%)." (PMID 40342430, 2025). "It is important to note, however, that findings across studies are not entirely uniform, and CRP is not a perfect stand-alone discriminator of postoperative infection." (PMID 41153812, 2025). "Performing serial CRP tests after 24–48 h after onset of infection increases the sensitivity and negative predictive value in diagnosing HAI." (PMID 39838378, 2025). "Recent evidence has identified IL-6, IL-8, and IL-10, alongside acute-phase reactants such as C-reactive protein (CRP) and procalcitonin (PCT), as promising biomarkers for early infection detection in neutropenic patients, supporting timely and targeted therapeutic interventions." (PMID 40647525, 2025). "Although IL- 6 release induces hepatic production of CRP and thus both metabolites are interconnected, the main diagnosis of infection was not a significant predictor of IL- 6 admission concentration, suggesting a distinct spectrum of both cytokines." (PMID 40275239, 2025). "Inflammatory markers showed a slight elevation in CRP levels, measured at 21.4 mg/L, which was expected in the early postoperative period and not indicative of infection." (PMID 40725788, 2025). "However, CRP and PCT levels in the infection group were significantly higher than in the control group on postoperative days 1, 2, 3, and 7 (P < 0.05)." (PMID 40160471, 2025).
infection (continued). "Although IL-6 did not outperform CRP as an early predictor for postoperative infection in our study, it would be premature to conclude that the predictive performance of both biomarkers is equal." (PMID 40549692, 2025). "CRP, an acute-phase reactant, has previously been identified as a predictor of SBP recurrence., reflecting both the inflammatory burden and, in some cases, incomplete infection control." (PMID 41353185, 2025). "Significant predictors for amputation included Wagner's grade ≥ 5, absent peripheral pulsation, clinical evidence of infection, and elevated levels of erythrocyte sedimentation rate and C-reactive protein." (PMID 39935923, 2025). "Such cases can be symptomatic and because CRP often remains normal in the absence of obstruction or infection, a CRP-first step is less informative for these presentations." (PMID 41204018, 2025). "The decision to withhold antibiotics was guided by the absence of clinical or biochemical evidence of active infection, supported by mild CRP elevation and lack of fever or oropharyngeal findings." (PMID 41147027, 2025). "Infection was considered present only when all three indicators (WBC, CRP, and ESR) were elevated." (PMID 40951409, 2025). "These proteins include C-reactive protein (CRP), serum amyloid A (SAA), and haptoglobin (Hp); these increase dramatically during acute inflammation, so these proteins are common indicators of inflammation, infection, or tissue damage." (PMID 40943382, 2025). "On postoperative day one, when a postoperative infection is unlikely to be present, the predictive performance of CRP as a single test in abdominal surgery was only moderate." (PMID 40549692, 2025). "In the absence of infection, the diagnosis of cytokine storm was made in our patient secondary to a constellation of clinical findings and elevations in cytokines, CRP, TG, and ferritin." (PMID 39820414, 2025). "C-reactive protein (CRP) is a blood marker commonly used to assess inflammation and infection." (PMID 40342577, 2025). "CRP levels of >10.0 mg/L are often considered indicative of acute inflammatory processes such as infections, inflammation, or other non-CVD conditions." (PMID 41281897, 2025). "The group with severe infection had greater values for WBC, AMC, PLT, CRP, ALT, GGT, creatinine, uRBCs, 24 h urine protein, cystatin C, LDH, corrected serum calcium, APTT, D-dimer, and IgE, used more types of immunosuppressants, and had a higher incidence of SRNS." (PMID 41291834, 2025). "The combination of PCT with CRP and WBC may enhance early infection prediction, although further validation in larger, multicenter cohorts is warranted." (PMID 40373822, 2025). "CRP levels were higher in severe cases (median: 46.8 mg/L, IQR: 12.5–60.8) compared to non-severe cases (27.0 mg/L, IQR: 2.3–51.9; p = 0.034), consistent with a more intense inflammatory response in severe infection." (PMID 41018059, 2025). "Infection was not suspected as the patient only had leucocytosis upon admission and a normal CRP, both increased and decreased spontaneously." (PMID 40634779, 2025). "Likewise, cytokines and chemokines including CRP, IL-15, IL-6, IP-10, MCP-1, TARC, MIP-1α, and IL-12p40 were increased following infection with WE-CL13-GP181M-185W-492I." (PMID 41086811, 2025). "Laboratory evaluation revealed no signs of infection, with C-reactive protein (CRP) at 1.2 mg/L, procalcitonin at 0.07 ng/mL, and white blood cell count (WBC) at 7.18×103/μL." (PMID 41362528, 2025). "Inflammatory markers, such as erythrocyte sedimentation rate (ESR), C-reactive protein (CRP), and white cell count (WCC), are routinely used when infection is suspected; however, they lack specificity and should be interpreted in conjunction with clinical and imaging findings." (PMID 41450376, 2025). "Especially in pneumonias or lower urinary tract infections without symptoms, CRP is able to initiate further diagnostics for the detection of these infections." (PMID 40001448, 2025).
infection (continued). "We think this finding has a profound impact on PJI management: 1) for those who presented with CRP > 35.43 and CAR > 0.847 before PRABCSI, more attention should be paid to evaluate whether the infection was controlled after PRABCSI." (PMID 41488484, 2025). "Routine CRP monitoring helps rule out infections, but investigating elevated CRP alone does not lead to earlier diagnosis." (PMID 40342430, 2025). "Another limitation is the absence of objective biomarker data (e.g., C-reactive protein, white blood cell count, procalcitonin) to confirm infection and assess treatment response." (PMID 40867977, 2025). "Even in Case 3, despite a dual infection, the infant’s CRP levels remained low; pertussis infections do not frequently elicit heightened acute-phase reactants, complicating diagnosis based on inflammatory markers." (PMID 40710034, 2025). "Although the median CRP levels were similar between the groups with severe and non-severe infections in our model—there were significant differences in their 95% CIs." (PMID 41291834, 2025). "Third, although inflammatory markers such as CRP or IL-6 were not available for the entire cohort, all patients with documented clinical or laboratory evidence of infection were excluded from the latter." (PMID 40970059, 2025). "In our patient, the constellation of dyspnoea, pleuritic pain, hypoxia, and bilateral ground-glass opacities on CTPA, together with low procalcitonin (0.07 μg/L), normal complement levels (C3: 1.29 g/L, C4: 0.47 g/L), and mildly raised CRP (23 mg/L), favored ALP over infection." (PMID 41287713, 2025). "Furthermore, the performance of ICIS was compared with that of the established biomarkers CRP and PCT, which are widely used in hospital laboratories for diagnosing infection." (PMID 40471473, 2025). "Third, while procalcitonin and CRP levels were analyzed, the absence of clinical outcome data limits the ability to correlate inflammatory markers with infection severity or prognosis." (PMID 39897275, 2025). "In addition, the inflammatory profile in HBV infection, commonly assessed by serum C-reactive protein (CRP), appears to vary depending on the phase of infection, with higher CRP levels reported during immune-active states and in association with liver damage." (PMID 41012636, 2025). "Both in cases without (p ≤ 0.001) and with further infection (p = 0.005), CRP levels increased significantly from pre- to postoperatively." (PMID 40001448, 2025). "This study aims to evaluate the clinical usefulness of serial CRP and WBC monitoring in culture‐positive acute hand infections and to determine whether biomarker profiles correlate with infection depth and treatment response." (PMID 41556000, 2025). "Elevated C-reactive protein (CRP) and ferritin levels have been found in patients with coinfection; however, elevation did not occur before the diagnosis of infection." (PMID 40416960, 2025). "Similarly, CRP in patients with GCE and infection on 1 day, 9–11 days, and 19–21 days was higher than in others." (PMID 40507570, 2025). "The absence of active infection preoperatively was supported by unremarkable CRP and interleukin-6 levels upon admission, as well as normal chest x-ray findings." (PMID 41395310, 2025). "Of these, 24 were excluded for being non-peer-reviewed publications, 18 lacked outcomes relevant to postoperative infections, and 20 provided incomplete or unclear data on CRP or NLR values." (PMID 41018345, 2025). "Consistently, elevated bio-ADM levels at baseline were associated with higher disease severity, as expressed in higher SOFA and APACHE scores, higher incidence of organ (in particular renal) dysfunction, and with higher levels of markers of infection and inflammation (PCT and CRP)." (PMID 40447978, 2025). "Among those with negative scan findings 40% were true negatives and the rest were likely negative due to normalized CRP level, a statistically significant marker of infection in this study." (PMID 41502998, 2025).